GAL (galanin and GMAP prepropeptide)
Diseases named in the same sentence as GAL in open-access papers (continued):
Sharing a sentence is not in itself a finding about the gene and the disease.
breast carcinoma (3 papers, 2019 to 2023). "GAL was also up-regulated in all three different settings: ER+ breast cancer, postmenopausal dense breasts, and premenopausal breasts." (PMID 37064098, 2023). "GAL expression alongside its receptors have been detected in several cancer forms including breast cancer and both pro- and anti-tumorigenic actions have been suggested." (PMID 37064098, 2023). "Of the 92 quantified proteins only two shared similar up-regulations in breast cancer, dense breast tissue, and in premenopausal breasts namely CTSH and GAL." (PMID 37064098, 2023). "Thus, it must be confirmed whether or not GAL plays an important role in breast cancer, and the proliferative/antiproliferative action of the peptide in bladder cancer, melanoma and cardiac and esophageal carcinomas must be investigated in-depth." (PMID 35954419, 2022).
dementia (3 papers, 2016 to 2025). Loss of intellectual abilities interfering with an individual's social and occupational functions. "Only a limited number of clinical studies have evaluated the therapeutic relevance of GAL in the other forms of dementia." (PMID 27110749, 2016). "Additionally, rutin exhibited the highest probability of activity (Pa = 0.541) for dementia treatment, followed by GAL (Pa = 0.458) and chlorogenic acid (Pa = 0.258)." (PMID 40430525, 2025). "The dementia model was induced by SCOP (100 μM), whereas GCEO and galantamine (GAL, 1 mg/L) were delivered to the SCOP-induced model." (PMID 36840131, 2023). "Recently, a clinical study was performed to investigate the influence of cholinesterase inhibitors including GAL, RIV and donezepil on sleep pattern and sleep disturbance in 87 mild to moderate stage dementia patients." (PMID 27110749, 2016).
gastritis (3 papers, 2014 to 2016). Inflammation of the stomach. "This fact may be a consequence of protective function of other bioactive substances such as PACAP, VIP, NO, and GAL in ASA-supplementation-induced gastritis, but this question needs further research." (PMID 24643520, 2014). "ASA- induced gastritis resulted in increased expression of NPY and GAL, as well as the novo-synthesis of nNOS and LENK in traced CCMG neurons." (PMID 26606050, 2015). "In summary, this study shows that ASA-induced gastritis in immature gilts results in increased expression of PACAP and de novo expression of VIP, NOS, and GAL in dorsal motor vagal neurons supplying the prepyloric region of the porcine stomach." (PMID 24643520, 2014). "Moreover, ASA- induced gastritis resulted in increased expression of NPY (76.59 ± 3.02%) and GAL (26.45 ± 2.75%) as well as the novo-synthesis of nNOS (6.13 ± 1.11%) and LENK (4.77 ± 0.42%) in traced CCMG neurons." (PMID 26606050, 2015). "ASA-induced gastritis led to the significant changes in the chemical coding of traced neurons, by reducing production of the catecholamine-synthesis tract enzymes and up-regulation of synthesis of neuropeptides involved in neuronal defence mechanisms (NPY, GAL, nNOS, LENK)." (PMID 26606050, 2015).
glioma (3 papers, 2020 to 2024). A benign or malignant brain and spinal cord tumor that arises from glial cells (astrocytes, oligodendrocytes, ependymal cells). "Most interestingly, expression of GAL and GALRs was observed in tumor-infiltrating immune cells, including neutrophils and glioma-associated macrophages/microglia." (PMID 32265844, 2020). "GAL‐positive subtypes tended to have higher cure rates, in accordance with similar results observed for GAL and its receptors in gliomas." (PMID 38738958, 2024). "Overall, the cellular heterogeneity of glioma subtypes was reflected by a heterogeneous pattern of expression of GAL and GALRs." (PMID 32265844, 2020). "Anterior pituitary gland (n = 7), pituitary adenoma (n = 9) and glioma of different WHO grades I–IV (n = 55) were analyzed for the expression of GAL and the three GALRs with antibodies recently extensively validated for specificity." (PMID 32265844, 2020). "The majority of gliomas showed focal GAL-immunoreactivity (71% of cases) and regions with diffuse GAL-staining (93% of cases)." (PMID 32265844, 2020). "To date, GAL peptide expression, GAL receptor binding and mRNA expression have been reported in glioma, meningioma, and pituitary adenoma." (PMID 32265844, 2020). "GAL-immunoreactivity was sparse in neutrophilic granulocytes in glioma (5% of 57 cases) and was only observed in subpopulations." (PMID 32265844, 2020). "In glioma, diffuse and focal GAL staining was noticed in the majority of cases." (PMID 32265844, 2020). "Corresponding to observations in glioma samples, receptor downregulation might also be a possible mechanism in pituitary adenoma to escape anti-proliferative effects of GAL." (PMID 32265844, 2020). "In accordance with this hypothesis, GAL suppressed proliferation of human U251 and T98G glioma cells via GAL1-R signaling." (PMID 32265844, 2020). "GAL blocked, through GAL1R, the proliferation of human glioma cell lines (U251, T98G) and tumor growth in nude mice." (PMID 35954419, 2022). "GAL inhibited the proliferation of glioma cells and tumor growth via GAL1R; a reduced level of GAL was observed in the cerebrospinal fluid of patients with glioblastoma, and GAL3R expression has been related to high-grade glioma: the line of research on glioma must be developed in the future." (PMID 35954419, 2022). "Glioma-associated macrophages (GAMs) are involved in tumor progression; although macrophages produce/secrete GAL, GAMs do not express GAL, but express GAL3R, and this means that GAL could regulate the activity of GAMs." (PMID 35954419, 2022).
head and neck cancer (3 papers, 2018 to 2023). A primary or metastatic malignant neoplasm affecting the head and neck. "In the context of tumors, GAL was found to promote tumor invasion via binding to its receptor, GALR2, in head and neck cancer." (PMID 36039037, 2023). "In head and neck cancer, the neuropeptide galanin (GAL) activates its receptor, GALR2, on cancer cells and stimulates the transcription of cyclooxygenase-2 and GAL itself." (PMID 36499024, 2022).
mood disorder (3 papers, 2019 to 2025). A cognitive disorder a disturbance in which the person's mood is hypothesized to be the main underlying feature. "Other authors have already demonstrated associations between GAL polymorphisms and mood disorders, but no studies have been done to date to test this possible association in a non-clinical, largely normal, healthy sample." (PMID 31881033, 2019). "As such, GAL and SPX are involved in similar processes, namely, in energy regulation, reproduction, stress responses and mood disorders." (PMID 35692389, 2022).
pituitary adenomas (3 papers, 2012 to 2021). "Mainly ACTH-secreting pituitary adenomas were GAL-positive, whereas growth hormone- and prolactin-secreting as well as non-functioning pituitary adenomas showed lower frequencies of GAL-immunoreactivity." (PMID 32265844, 2020). "This is in accordance with GAL mRNA expression data, which showed lower GAL expression levels in 10 out of 13 pituitary adenomas." (PMID 32265844, 2020). "In our study, 8 of 9 cases of pituitary adenoma had at least some areas with diffuse GAL-immunoreactivity." (PMID 32265844, 2020). "While high focal GAL immunoreactivity was detected in up to 40% of cells in the anterior pituitary gland samples, only one pituitary adenoma showed focal GAL expression, at a low level." (PMID 32265844, 2020). "Out of 9 pituitary adenomas, only one, a null-cell tumor (case 7), was positive for GAL, showing medium to strong focal GAL-immunoreactivity in 2% of the tumor cells." (PMID 32265844, 2020). "A study found that GAL and ACTH were co-expressed in human pituitary and pituitary adenomas, and suggested that GAL may be locally involved in the regulation of the HPA axis." (PMID 34905486, 2021). "Our data on the expression of GAL in pituitary adenoma correlate with previous published data, where 77% of patients with Cushing's disease (ACTH-secreting), 25% of patients with acromegaly (growth hormone-secreting), 13% of prolactinomas and 34% of non-functioning tumors expressed GAL." (PMID 32265844, 2020). "Furthermore, it also seemed that the tumor itself reduced GAL expression, as only 11% of pituitary adenoma showed focal GAL staining, in contrast to 100% of healthy pituitary glands." (PMID 32265844, 2020). "Eight pituitary adenomas displayed diffuse GAL-immunoreactivity with low to medium intensity." (PMID 32265844, 2020). "Furthermore, GAL-immunoreactivity was much lower in pituitary adenoma as in the anterior pituitary gland." (PMID 32265844, 2020). "The percentage of GAL-positive cases was dependent on the type of pituitary adenoma." (PMID 32265844, 2020). "GAL-immunoreactivity was absent in tumor-associated immune cells in pituitary adenoma." (PMID 32265844, 2020). "Three pituitary adenomas [cases 3 (FSH), 5 (null cell), 6 (STH, prolactin)] had <10 GAL-positive stained cells and the remaining five were negative for focal GAL staining." (PMID 32265844, 2020).
squamous cell carcinoma (3 papers, 2015 to 2023). A carcinoma arising from squamous epithelial cells. "For example, in squamous cell carcinoma, high GAL levels are associated with poor survival outcome and cancerogenic immune escape, as well as accelerated cancer progression." (PMID 37443714, 2023). "Moreover, in samples from clinical squamous cell cancer, six genes (GAL, GSTP1, MRPL11, MRPL21, SF3B2, and YIF1A) at 11q13.1–13.3 and one gene (GALR1) at 18q23 showed significant differences in expression between normal and tumor samples." (PMID 31552180, 2019).
type 2 diabetes (3 papers, 2014 to 2021). "Impaired glucose tolerance is a prediabetic stage since it appears before the development of type 2 diabetes and a high level of plasma GAL is related to the development of impaired glucose tolerance." (PMID 33802616, 2021). "In healthy subjects and in those suffering from type 2 diabetes, a positive relationship between blood glucose and GAL levels has been reported." (PMID 33802616, 2021). "Decreased expression of NPY and GAL corresponded with altered feeding behaviors and weight changes in a type 2 diabetes rat model." (PMID 25197671, 2014). "Non-pregnant women suffering from type 2 diabetes showed a high level of circulating GAL and this level was positively correlated with the level of blood glucose." (PMID 33802616, 2021).
adenoma (2 papers, 2020 to 2022). A neoplasm arising from the epithelium. "The GAL level was low in GH secreting adenomas, but the level of the peptide was high in corticotroph adenomas." (PMID 35954419, 2022). "GAL exerted a tumor-reducing effect in experimental murine models (gastrointestinal cancer), but in other models (adenoma formation), GAL promoted cell proliferation and tumor formation." (PMID 35954419, 2022). "In ACTH-secreting adenoma, GAL seems to serve as a biomarker, with GAL levels being inversely correlated with tumor volume." (PMID 32265844, 2020). "GAL expression is related to smaller adenomas and better prognosis." (PMID 35954419, 2022).
bladder (2 papers, 2015 to 2021). "Callsen-Cencic and Mense revealed that GAL inhibits presynaptically the release of SP and CGRP from bladder capsaicin-sensitive primary afferents following mustard oil-induced inflammation of the urinary bladder." (PMID 26580655, 2015).
brain injuries (2 papers, 2017 to 2018). "In turn, GAL is known from neuroprotective functions in the central and peripheral nervous system, which have primarily been described during brain injuries and neurodegenerative diseases." (PMID 30154361, 2018). "GAL has been reported to have neuroprotective roles in several cases, such as traumatic brain injury, beta-amyloid poisoning, glutamate induced excitotoxicity, high-glucose induced apoptosis and shear stress induced injury." (PMID 28203483, 2017).
brain tumors (2 papers, 2020 to 2021). "The aim of the present study was to examine the expression of GAL and GALRs in different brain tumors by immunohistochemistry." (PMID 32265844, 2020). "The aim of the present study was to elucidate the expression of GAL and GALRs in different human brain tumors by immunohistochemistry (IHC) with carefully validated antibodies." (PMID 32265844, 2020). "Our findings correlate with our previous study, where GAL staining in glial cell bodies was found in 18 out of 20 (90%) human brain tumors, including glioblastoma multiforme (WHO grade IV), meningioma (WHO grade I-II), and gliosarcoma (WHO grade IV)." (PMID 32265844, 2020). "Additionally, GAL-positive corticotroph adenomas were associated with a higher cure rate in patients, suggesting clinical relevance for GAL in this brain tumor type." (PMID 32265844, 2020).
cholestasis (2 papers, 2013 to 2023). Impairment of the bile flow caused by obstruction within the liver, or outside the liver in the bile duct system. "Regarding GAL receptors, GAL1-R was previously shown to mediate GAL-induced cholangiocellular hyperplasia during cholestasis." (PMID 37443714, 2023). "In the tunica adventitia, GAL expression in the veins was, on average, 75% lower in cholestasis patients compared to the healthy controls (p = 0.0051)." (PMID 37443714, 2023). "An additional analysis of cholangiocytes in cholestasis and pCCA revealed alterations in the expression of the GAL system that mainly affected the receptors." (PMID 37443714, 2023). "One of these factors is GAL, which is increased in serum and liver after bile duct obstruction in rats." (PMID 37443714, 2023). "A limitation of this study is that the results were solely obtained via immunohistochemistry, as we intended to provide a first overview of the expression pattern of the GAL system in the healthy human biliary tract, cholestasis and CCA." (PMID 37443714, 2023). "In cholestasis patients in particular, GAL expression was reduced by more than 78% in mucosal arteries (PIT+C, p = 0.0025) and by 85% in arteries within the tunica adventitia (PIT+C, p = 0.0051)." (PMID 37443714, 2023). "GAL expression was reduced by 56% in capillaries of the tunica adventitia in cholestasis (p = 0.0152)." (PMID 37443714, 2023). "Further, we elucidated whether the cellular expression of GAL and its receptors is altered in cholestasis." (PMID 37443714, 2023). "Our study sought to characterise GAL and GAL1–3 receptor (GAL1–3–R) expression in the healthy human bile duct, in cholestasis and pCCA." (PMID 37443714, 2023). "In biliary nerve fibres, a trend towards increased GAL expression was observed in large (PIT-C: 56%, PIT+C: 60%) and small (PIT-C: 21%, PIT+C: 29%) nerve fascicles in PIT with and without cholestasis." (PMID 37443714, 2023). "Like in arteries, GAL expression in PIT both with and without cholestasis (PIT+C and PIT-C) was lower within mucosal veins compared to the healthy controls (PIT+C: 40%, p = 0.0303; PIT-C: 36%; p = 0.0383)." (PMID 37443714, 2023).
colon adenocarcinoma (2 papers, 2013 to 2020). "Because GAL inhibits cell proliferation, an increase in its synthesis may be associated with the activation of protective mechanisms in patients with colon adenocarcinoma." (PMID 33552060, 2020). "Additionally, GAL overexpression was noted in all colon adenocarcinoma cells tested (LOVO, HCT116, SW480, and SW620 cells), but not in the A549 lung cancer cell line, OVCAR3 and SKOV3 ovarian cancer cell lines, or the HS1 testicular cancer cell line." (PMID 33552060, 2020).
corticotroph adenomas (2 papers, 2020 to 2022). "GAL has been observed in 84% of the corticotroph cell tumors associated with Cushing’s disease, although another study has reported that GAL did not play an important pathophysiological role in this disease because corticotroph adenomas can function irrespective of the presence of GAL." (PMID 35954419, 2022).
gastric tumour (2 papers, 2018 to 2023). "In healthy tissues, distal to the gastric tumour, neuronal secreted GAL was reported to enhance cell survival and protect benign cells from caspase-mediated cell death." (PMID 37443714, 2023).
gestational diabetes (2 papers, 2016 to 2021). Carbohydrate intolerance first diagnosed during pregnancy. "The circulating GAL level was also higher in pregnant women with gestational diabetes mellitus than in pregnant women with normal glucose tolerance." (PMID 33802616, 2021). "Moreover, a positive correlation was observed between the levels of glucose and GAL in pregnant women with gestational diabetes mellitus." (PMID 33802616, 2021).
glioblastoma (2 papers, 2020 to 2022). The most malignant astrocytic tumor (WHO grade IV). "GAL has been reported in gliosarcoma and glioblastoma multiforme; in the latter, the most abundant receptor found was GAL1R, followed by GAL3R and GAL2R." (PMID 35954419, 2022). "In glioblastoma multiforme (WHO grade IV), GAL-positive cell staining was observed in 75% of cases (<1–30% of tumor cells)." (PMID 32265844, 2020).
Hirschsprung disease (2 papers, 2018 to 2020). Hirschsprung disease (HSCR) is a congenital intestinal motility disorder that is characterized by signs of intestinal obstruction due to the presence of an aganglionic segment of variable extent in the terminal part of the colon. "In a recent study, we have shown that genetic markers within GAL, GAP43 and NRSN1 contribute to the altered HSCR susceptibility, and importantly, the interaction networks among GAP43, NRSN1 and PTCH1 confer an increased risk to Hirschsprung disease." (PMID 32139661, 2020).
inflammatory bowel disease (2 papers, 2016 to 2021). A spectrum of small and large bowel inflammatory diseases of unknown etiology. "Furthermore, in the pathogenesis of inflammatory bowel disease, both GAL and hormones are involved in the communication between the autonomous nervous system and the neurons of the enteric nervous system (ENS)." (PMID 27293908, 2016).
laryngeal carcinoma (2 papers, 2018). Carcinoma that arises from the laryngeal epithelium. "Recurrence events were significantly associated with HCRT methylation (P = 0.005) and GAL methylation (P = 0.031) in laryngeal cancer patients." (PMID 29682090, 2018). "Similar findings were observed for HCRT and GAL in patients with laryngeal cancer and oropharyngeal cancer, respectively." (PMID 29682090, 2018). "Methylation of the GAL gene had a significantly lower frequency in hypopharyngeal cancers when compared to laryngeal cancers and oral cavity cancers (p = 0.035 and p = 0.007, respectively)." (PMID 29361757, 2018). "Moreover, to our knowledge, our study is the first to suggest that TAC1, HCRT, and GAL methylation is associated with worse DFS and that this may be a critical event in oral cancers, laryngeal cancers, and oropharyngeal cancers, respectively." (PMID 29682090, 2018). "Notably, the less frequently methylated genes (less than 30%) were as follows: CDH13, p16, MGMT, GAL, NPY, GALR2, and VEGFR3 for hypopharyngeal cancers; CDH13, p16, RASSF1A, GAL, NPY, and NPY1R for laryngeal cancers; and CDH13 and GAL for oral cavity cancers." (PMID 29361757, 2018).
lung disease (2 papers, 2023 to 2025). "Thus, it is possible to propose a potential connection between GAL and the inflammatory processes associated with pulmonary diseases." (PMID 40048451, 2025).
melanoma (2 papers, 2022 to 2023). A malignant, usually aggressive tumor composed of atypical, neoplastic melanocytes. "The expression of GAL has been reported in melanoma, and human Bowes melanoma cells expressed GAL1R." (PMID 35954419, 2022). "A recent study by Zavadinack and colleagues demonstrated that polysaccharides α-D-galactan (GAL-Am) and β-D-glucan (GLC-Am), extracted from Amanita muscaria fruiting bodies, exhibited selective reduction in proliferation against the B16–F10 melanoma cell line." (PMID 37836667, 2023).